ENSG00000288643 (novel transcript)
Gene: Protein-coding gene on chromosome 5 (62,306,206 to 62,537,249, forward strand). Ensembl gene ENSG00000288643.
Genetic constraint (gnomAD): Missense variants: 28 observed, 25.04 expected, observed/expected ratio (o/e) 1.12, 90% interval 0.83 to 1.53. Synonymous variants: 13 observed, 11.24 expected, observed/expected ratio (o/e) 1.16, 90% interval 0.75 to 1.76.